IL15 (interleukin 15)
Diseases named in the same sentence as IL15 in open-access papers (continued):
Sharing a sentence is not in itself a finding about the gene and the disease.
colorectal cancer (continued). "In a study of colorectal carcinoma (CRC), tumors that lost IL-15 expression had lower levels of immune activation as measured by T and B cell abudance." (PMID 30477280, 2018). "Among breast and colorectal cancer survivors, randomization to 12 weeks of aerobic exercise increased LIF and IL‐15, whereas randomization to 12 weeks of metformin reduced apelin and IL‐15." (PMID 38887915, 2024). "CD16 × IL-15 × Epcam TriKE, CD16 × IL-15 × CD133 TriKEs, and CD16 × IL-15 × CD133 × Epcam TetraKE are under investigation to treat colorectal cancer and have shown significantly enhanced cytokine secretion, NK cell proliferation, and lytic degranulation." (PMID 32140153, 2020). "Interleukin-15 (IL-15) is a cytokine that has demonstrated a pronounced protective effect against CPT-11-induced intestinal toxicity and has the potential to moderately boost the antitumor efficacy in advanced colorectal cancer models." (PMID 40143136, 2025). "In patients with colorectal carcinoma, absence of IL-15 expression correlated with decreased immune activation assessed by T and B cell abundance, and predicted worse prognosis." (PMID 31740623, 2019). "Similarly, next-generation IL-15-armored, FAP-targeting CAR-iNKT therapy MiNK-215, designed to target the tumor stroma, further enhanced endogenous anti-tumor activity in human organoid models of treatment-resistant colorectal cancer liver metastases." (PMID 40718496, 2025).
lung carcinoma (31 papers, 1998 to 2025). "In patients with lung cancer, high concentrations of intratumoral IL-15 are associated with a worse prognosis." (PMID 39199571, 2024). "A high intratumor expression of IL-15 and serum IL-15R has been associated with poor survival in lung cancer and head and neck cancers, respectively." (PMID 36831406, 2023). "Identification of IL15 as activated upstream regulator for ADC agrees with the knowledge that inflammatory pathways are implicated in lung cancer development and IL15-mediated cross-talk between patrolling monocytes and NK cells is involved in metastasis formation." (PMID 35512017, 2022). "Lower levels of EGF, IL-15, and IL-1ra may be involved in the activation of apoptosis or in the impairment of immunosurveillance, two mechanisms that lead to a higher lung cancer risk." (PMID 23577098, 2013). "The lower levels of IL-15 found in subjects with emphysema could possibly reflect impaired tumour immunosurveillance and thus be implicated in their well-known increased risk of lung cancer." (PMID 23577098, 2013). "A few recent cases, such as those involving inhaled IL-15 therapy in canine lung cancer, have shown promising outcomes." (PMID 41302038, 2025). "Palbociclib induces Rb-mediated senescence and NF-κB-driven pro-inflammatory SASP in tumor cells, including TNF-α and IL-15, thereby leading to NK cell infiltration in lung cancer mouse model." (PMID 41463246, 2025). "To date, the administration of recombinant human IL‐15(rhIL‐15) and IL‐15 agonists has been validated by multiple preclinical and clinical trials in various types of cancers but is limited in lung cancer immunotherapy." (PMID 40799128, 2025). "(iC9-GD2.CAR IL-15 T-cells) in patients with advanced lung cancer including SCLC (NCT05620342), CAR T-cells have shown promising results in preclinical studies." (PMID 39897044, 2025). "IL‐15 superagonists have shown efficacy across various cancers, yet their effects in lung cancer immunotherapy remain underexplored." (PMID 40799128, 2025). "Our results align with these prior researches, underscoring the potent antitumor efficacy of SHR‐1501 as a novel IL‐15 super‐agonist in tumor‐bearing mice models of lung cancer cell lines." (PMID 40799128, 2025). "Recent findings indicate that tissue‐resident lung NK cells exhibit enhanced responsiveness to IL‐15, suggesting its potential as a viable option for patients with lung cancer or other malignancies." (PMID 39588940, 2024). "The utilization of IL‐15‐stimulated NK cells presents a promising allogeneic approach in the treatment of lung cancer patients." (PMID 39588940, 2024). "We would predict, therefore, that the IL-15 component of this TriKE, which targets lung cancer, would also enhance infiltration of NK cells directly into the tumor, but this remains to be shown." (PMID 36911670, 2023). "According to single‐cell investigations in lung cancer, mregDCs can release IL‐15 and promote tissue‐resident T‐cell function." (PMID 36808888, 2023). "PLD is involved in the induction of the preresorptive cytokine, IL-6, in osteoblasts and is required for lung cancer-derived IL-8-induced osteoclastogenesis and IL-15-mediated osteoclastogenesis in RASF." (PMID 32370217, 2020). "Taken together, these data support the notion that DNTs can target lung cancer cells via different mechanisms that can be augmented by IL-15, and the expression levels of ligands and receptors on cancer cells dictate DNT cell mode of action." (PMID 30670085, 2019). "DNTs have the potential to be used as a novel adoptive cell therapy for lung cancer either alone or in combination with IL-15." (PMID 30670085, 2019). "CIK cells stimulated with a combination of IL-2 and IL-15 have shown greater cytotoxicity against human lung cancer cells." (PMID 29184163, 2017). "IL-15 treatment significantly increased tumor cell growth in the A549, H1299 cell line-derived xenograft model, and two lung cancer PDX model in NSI mice." (PMID 29255466, 2017).
lung carcinoma (continued). "To explore the possibility that IL-15 promotes lung cancer cell growth, we established cell line-derived xenograft and PDX models with NOD-SCID-IL2Rg−/− (NSI) mice." (PMID 29255466, 2017). "In this study, we use immunodeficient mice lacking T cells, B cells, and NK cells to study IL-15 and identify an important role for IL-15 in promoting lung cancer growth." (PMID 29255466, 2017). "Recently, a study demonstrated that an adenovirus vector expressing IL15 gene can inhibit lung cancer in mouse." (PMID 19422685, 2009). "Although adenovirus vector expressing IL15 gene can inhibit mouse lung cancer, it is difficult to be applied on human cancer treatment due to adenovirus vector-induced cytotoxicity and inflammatory response." (PMID 19422685, 2009). "Effective killer induction by IL-15 was observed even in blood MNCs and pleural MNCs from the site of tumour growth in advanced lung cancer patients." (PMID 9744501, 1998). "In the case of MNCs from lung cancer patients, IL-10 production was more prominent when cells were incubated with IL-2 than with IL-15." (PMID 9744501, 1998). "IL-15 T-cells) among patients with advanced lung cancer, including SCLC (NCT05620342), CAR." (PMID 39897044, 2025). "In this study, we found that IL-15 was expressed by lung cancer cells." (PMID 38637902, 2024). "However, there was a significant increase in all measures of NK cell proliferation for lung cancer patients treated with TriKE compared to unstimulated controls, suggesting that NK cells in these patients can still respond to IL-15 stimulation." (PMID 36911670, 2023). "In addition, clinical studies have reported a correlation between high intra-tumor IL-15 concentrations and poor clinical outcomes in patients with lung cancer, which is contrary to our results." (PMID 36467072, 2022). "A previous study indicated that IL-15–primed NK cel ls could survive in the ROS-rich tumor microenvironment, which is conducive to those smokers with lung cancer." (PMID 33771173, 2021). "Additionally, these results indicate that myeloid CD45+ CD215+ cells play an important role in lung cancer progression under IL-15 stimulation." (PMID 29255466, 2017). "A gene therapy for mouse lung cancer using an adenovirus vector expressing IL15 has been reported." (PMID 19422685, 2009). "Previous study has used adenoviral vector expressing IL15 gene for mouse lung cancer treatment." (PMID 19422685, 2009). "Moreover, according to a single‐cell study of lung cancer, Trm expansion and homeostatic survival may be facilitated by mregDCs through IL‐15 and IL‐15R binding, which are vital cytotoxic immune cells and are responsible for the effects of immunotherapy." (PMID 36808888, 2023). "Furthermore, addition of either recombinant sTRAIL or IL-15 conditioned DNT cell culture supernatant induced death of lung cancer cell lines that expressed TRAIL receptors, which could be blocked by anti-TRAIL neutralizing antibody." (PMID 30670085, 2019). "Given that several NSCLC cell lines show some resistance to DNT-mediated cytolysis, and lung cancer xenograft growth was modestly inhibited by DNTs, we determined whether IL-15, a well-known myeloid derived immune modulator, could augment DNT-mediated anti-tumor activity." (PMID 30670085, 2019). "In our previous study, a new method was developed to prime and propagate CIK cells by the combination of IL-2 and IL-15, and this kind of CIK cells had enhanced antitumor effect on lung cancer." (PMID 34540187, 2021). "Our data indicates that the cam1615B7H3 TriKE delivers a specific IL-15 signal to the NK cells, preventing off target toxicities, and also mediates ADCC against a variety of adenocarcinoma cell lines in the ovarian, prostate, and lung cancer settings." (PMID 32961861, 2020). "IL-5 production was observed in MNCs from lung cancer patients stimulated with IL-2, but not with IL-15." (PMID 9744501, 1998).
lung carcinoma (continued). "Similarly, in lung cancer models, GD2-specific CAR-T cells expressing IL-15 and incorporating an inducible caspase-9 (iC9) safety switch demonstrated sustained persistence and robust antitumor activity, consistent with findings in other GD2-expressing tumor models." (PMID 40771804, 2025). "Interestingly, even though NKp44 was upregulated by IL-15, DNTs did not utilize this receptor in cytolysis of the three lung cancer cell lines tested." (PMID 30670085, 2019). "In this study, we examined the effect of IL-15 on induction of non major histocompatibility complex (MHC)-restricted killer activity and of type 2 cytokine production by peripheral blood and pleural mononuclear cells (MNCs), from 34 lung cancer patients and 20 control subjects." (PMID 9744501, 1998).
prostate carcinoma (27 papers, 2000 to 2025). A carcinoma that arises from epithelial cells of the prostate gland. "Co-expression of IL-15 and membrane-associated IL-15Rα by an adenovirus system exerted stronger antitumor effects than IL-15 alone against murine breast and prostate cancer." (PMID 34439192, 2021). "IL-15 production pathway, one of the significant pathways, is known to be associated with prostate cancer." (PMID 31748686, 2019). "IL-15 in combination with the STING agonist (ADU-S100) induced prostate cancer cell death by increasing natural killer cells." (PMID 39049995, 2024). "The anti-tumor potential of recombinant IL-15 has been demonstrated in murine tumors including prostate cancer." (PMID 37465665, 2023). "In an in vitro prostate cancer-lymphocyte co-culture model, we have shown that IL-15 combined with a STING agonist led to enhanced cancer cell killing due to activation of NK cells." (PMID 37465665, 2023). "To activate multiple immune-stimulatory pathways in the hostile prostate cancer microenvironment, we used a combination of cytotopically modified interleukin-15 (cyto-IL-15) with the stimulator of interferon genes (STING) agonist, ADU-S100." (PMID 37465665, 2023). "We previously showed that combination of IL-15 with an ADU-S100 analog in an in vitro prostate cancer-lymphocyte co-culture model increased NK cells cytotoxicity and led to notable cancer cell killing." (PMID 37465665, 2023). "IL-15 can effectively reduce tumor growth in many preclinical tumor models including prostate cancer." (PMID 34778376, 2021). "In prostate cancer-lymphocyte co-cultures we now show that combination of IL-15 and the STING agonist ADU-S100 analog induces a marked killing of cancer cells above that seen with IL-15 or ADU-S100 alone." (PMID 33777767, 2021). "Our laboratory has shown that IL-15 is the only protein among a panel of several cytokines that was able to expand and activate immune cells in vitro; this effect was increased when prostate cancer cells were present." (PMID 34778376, 2021). "Recently, the effect of cytotopic IL-15 in the reduction of prostate cancer tumors in mice models has been demonstrated by our laboratory." (PMID 34778376, 2021). "As expected, an increase in the levels of IFN-γ was observed when PBMCs alone or co-cultured with prostate cancer cells were incubated with IL-15." (PMID 33777767, 2021). "Elevated expression of IL‐7 and IL‐15 in prostate tissues and its increased serum level was confirmed in patients with early‐stage prostate cancer." (PMID 26880719, 2016). "Stimulation of DC for 24 hours with CD40 ligand (CD154), IL-12 or IL-15 prior to their co-incubation with prostate cancer cells resulted in a significant increase in DC survival in the tumour microenvironment." (PMID 10945499, 2000). "Stimulation of DC by CD154, IL-12 or IL-15 leads to an increased expression of the anti-apoptotic protein Bcl-x L and increased resistance of DC to prostate cancer-induced apoptosis." (PMID 10945499, 2000). "Likewise, specific cytokines such as IL-6, TNF-a, IL-15, and IL-1 have been postulated to promote or inhibit cancer cachexia and prostate cancer by affecting several aspects of lipid metabolism." (PMID 38916917, 2024). "Promising effect against prostate cancer by modulating IL-15 level and MDSC activity." (PMID 36969071, 2023). "In addition, a phase I trial demonstrated the antitumor effect of Agaricus bisporus on prostate cancer by modulating IL-15 level and MDSC activity." (PMID 36969071, 2023). "Moreover, the efficacy of different doses of cyto-IL-15 was explored in vivo in a syngeneic subcutaneous prostate cancer mouse model." (PMID 34778376, 2021). "The purified IL-15 was then conjugated to a cytotopic peptide to allow anchoring of IL-15 to cell membranes (cyto-IL-15) and its activity and efficacy were investigated in vitro and in vivo in a prostate cancer murine model." (PMID 34778376, 2021).
prostate carcinoma (continued). "Moreover, this study further highlights the potential of IL-15 as an effective immunotherapy for the treatment of patients with prostate cancer." (PMID 34778376, 2021). "Finally, prostate cancer cells express a trans- membrane IL-15, anchored in a IL-15R-independent fashion, which can participate in reverse signaling and/or act in a juxtacrine fashion promoting the development of bystander cells." (PMID 18493613, 2008). "In the current study, the membrane-localizing cyto-IL-15 was combined with the STING agonist ADU-S100, and their efficacy was investigated in both syngeneic and humanized prostate cancer murine models." (PMID 37465665, 2023). "In conclusion, our study evaluated the combination of the membrane localizing cyto-IL-15 with the STING agonist ADU-S100 both administered intratumorally, in three different murine prostate cancer models." (PMID 37465665, 2023). "In the present study, cyto-IL-15 combined with the STING agonist ADU-S100 led to significant anti-tumor efficacy and survival benefits in murine prostate cancer models." (PMID 37465665, 2023). "Recently, our group developed an HLA class I-positive NK feeder cell line originating from the adherent prostate carcinoma cell line PC3 and genetically engineered to express IL-2, 4-1BBL and a membrane-bound form of IL-15 (PC3PSCA-IL-2-4-1BBL-mIL-15d)." (PMID 35628668, 2022). "To conclude, our study shows that the combination of IL-15 and ADU-S100 analog induces an activation of NK cells, and a resulting prostate cancer cell death much greater than either two agents used separately." (PMID 33777767, 2021). "IL-15 also promoted invasion of many tumor cells through activation of JAK/STAT signaling pathway, such as head and neck cancer cells, prostate cancer cells." (PMID 33557944, 2021). "NK-92 cells expressing a first-generation EpCAM-specific CAR or coexpressing IL-15 and a second-generation EpCAM-specific CAR with intracellular signaling domains of CD28 were also developed to treat prostate cancer in mouse models." (PMID 30410941, 2018). "In this study, to identify prostate cancer treatments that are not only curative but also generate long-term immunoprotective responses, the potential of combining ADU-S100 with the membrane-localizing cyto-IL-15 was investigated in vivo." (PMID 37465665, 2023). "We therefore performed in vitro co-culture experiments of prostate cancer cells with non-adherent peripheral blood mononuclear cells (PBMCs), treated with either IL-15 alone or a combination of IL-15 and the ADU-S100 analog." (PMID 33777767, 2021). "In summary, we propose that the combination of IL-15 and the sting agonist ADU-S100 analog may be potently effective in treatment of prostate cancer." (PMID 33777767, 2021). "A preclinical study showed reduced tumor growth and increased immune cell infiltration in a mouse model of prostate cancer with IL-15 overexpression 2.5-fold and 2.7-fold higher numbers of CD8+ T cells and NK cells, respectively than in mice in the model without IL-15 injection." (PMID 36467072, 2022). "It has been previously shown by our group that IL-15, unlike other therapeutic cytokines such as IL-2 and IL-12, can stimulate expansion and activity of CD8 T cells and NK cells in vitro when they are exposed to prostate cancer cells." (PMID 33777767, 2021).